NR5A2 (nuclear receptor subfamily 5 group A member 2)
Diseases named in the same sentence as NR5A2 in open-access papers (continued):
Sharing a sentence is not in itself a finding about the gene and the disease.
pancreatic cancer (26 papers, 2011 to 2024). "Other studies have revealed that nuclear receptor subfamily 5 group A member 2 (NR5A2) haploinsufficiency has been seen associated with chronic pancreatitis and pancreatic cancer." (PMID 39882037, 2024). "In line with this notion, a genome-wide association study identified multiple pancreatic cancer susceptibility loci, including several SNPs located within a region on chromosome 1q32.1 where NR5A2 resides." (PMID 38012687, 2023). "Recently, single nucleotide polymorphisms in NR5A2 have been associated with the risk of pancreatic cancer development." (PMID 33850096, 2021). "Our analysis showed a significant interaction between poor oral hygiene and NR5A2 rs2816938 on pancreatic cancer risk." (PMID 32456644, 2020). "The interaction between poor oral hygiene and NR5A2 rs2816938 pointed toward the role of inflammation pathways in the oncogenesis of pancreatic cancer, although the biological mechanism underlying this interaction requires further investigation." (PMID 32456644, 2020). "These SNPs represent independent risk variants at previously identified pancreatic cancer risk loci on chr1q32.1 (NR5A2), chr8q24.21 (MYC) and chr5p15.33 (CLPTM1L-TERT) as per analyses conditioned on previously reported susceptibility variants." (PMID 27579533, 2016). "In conclusion, our case-control study found that rs3790844 in the NR5A2 gene is associated with pancreatic cancer risk in Japanese subjects." (PMID 26592175, 2015). "Loss of acinar NR5A2 was found to accelerate the development of oncogenic Kras driven acinar to ductal metaplasia and pancreatic cancer precursor lesions." (PMID 26592175, 2015). "We therefore examined the association between 2 SNPs (rs3790843 and rs3790844) in the NR5A2 gene and the risk of pancreatic cancer using data collected from a genetic case-control association study of Japanese subjects." (PMID 26592175, 2015). "Our case-control study found that rs3790843 and rs3790844 in the NR5A2 gene are associated with pancreatic cancer risk in Japanese subjects." (PMID 26592175, 2015). "In this genetic case-control association study, we genotyped 2 GWASs-identified SNPs (rs3790843 and rs3790844) in the NR5A2 gene and examined their association with pancreatic cancer risk." (PMID 26592175, 2015). "Of the 5 highly significant single nucleotide polymorphisms (SNPs) on 1q32.1 that map to NR5A2, rs3790844 showed the strongest association with pancreatic cancer, with a per-allele OR of 0.77 (95% CI: 0.71–0.84)." (PMID 26592175, 2015). "A recent genome-wide association study (GWAS) identified rs3790844 and rs3790843, located in the first intron of NR5A2 in 1q32.11, as associated with pancreatic cancer susceptibility." (PMID 25514243, 2014). "Single nucleotide polymorphisms (SNPs) in ABO, sonic hedgehog (SHH), telomerase reverse transcriptase (TERT), nuclear receptor subfamily 5, group A, member 2 (NR5A2) were found to be associated with pancreatic cancer risk." (PMID 22125638, 2011). "Several single nucleotide polymorphisms (SNPs) in the gene regions of ABO, sonic hedgehog (SHH), telomerase reverse transcriptase (TERT), nuclear receptor subfamily 5, group A, member 2 (NR5A2) were found to be associated with pancreatic cancer risk." (PMID 22125638, 2011). "Although the overexpression of NR5A2 accelerates malignant processes such as proliferation and invasion in pancreatic cancer, the loss of NR5A2 expression limits recovery from injury in pancreatitis, which in turn increases the risk of pancreatic ductal adenocarcinoma." (PMID 38358044, 2024). "Interestingly, “pancreatic cancer” and “uric acid levels” GWAS traits were connected through NR5A2, which is also linked to “chronic inflammatory diseases” and “lung carcinoma” traits." (PMID 33517887, 2021). "In addition, NR5A2 heterozygosity cooperated with Kras mutation in the oncogenesis of pancreatic cancer." (PMID 32456644, 2020).
pancreatic cancer (continued). "Further exploration of genetic variation in the NR5A2 gene and its effects on gene function could improve our understanding of pancreatic cancer pathogenesis and contribute to identifying high-risk individuals." (PMID 26592175, 2015). "For example NR5A2 plays an important role in transcriptional activation of the adiponectin gene, an adipocyte-secreted hormone, that has been proposed to be a biological link between obesity and increased risk of pancreatic cancer." (PMID 22125638, 2011). "A previous study reported that NR5A2 knockdown in pancreatic cancer led to an increase in the expression level of E‐cadherin and a decrease in the expression levels of snail and vimentin, suggesting that NR5A2 is involved in the EMT process." (PMID 38358044, 2024). "For instance, in a study of pancreatic cancer, activation of the BRD4 gene in cancer cells causes NR5A2 to be transcribed and upregulated, thus promoting pancreatic cancer progression." (PMID 38358044, 2024). "For instance, NR5A2 has been found to contribute to the malignancy of pancreatic cancer through an increase in the translational activity of β‐catenin and expression of its target genes." (PMID 38358044, 2024). "Nonetheless, experiments employing immortalized pancreatic cancer cell lines demonstrated that inhibiting NR5A2 significantly suppressed cell proliferation, indicating its role in tumor growth." (PMID 38012687, 2023). "Mechanistically, we show for the first time that NR5A2 promotes stemness in pancreatic cancer cells via enhanced expression of SOX2 (Sex-determining region Y (SRY)-Box2)." (PMID 38012687, 2023). "In the adult pancreas, NR5A2 is essential for normal pancreatic function, while in pancreatic cancer, its role is more complex, with evidence suggesting it can both promote and inhibit cancer progression." (PMID 38012687, 2023). "In previous studies using immortalized cancer cell lines, NR5A2 was shown to regulate the proliferation of bulk pancreatic cancer cells." (PMID 38012687, 2023). "NR5A2 has been established as a promising therapeutic target due to its known role in pancreatic cancer, including cell cycle regulation and early development." (PMID 36209277, 2022). "Taken together, these results suggest that BRD4 upregulates GDF15 by inducing NR5A2 expression in pancreatic cancer cells." (PMID 33850096, 2021). "To elucidate the biological role of NR5A2 in pancreatic cancer cells, we generated NR5A2 knockdown cell lines with two independent shRNAs in AsPC-1 and HPAC cells." (PMID 33850096, 2021). "Western blot and RT-qPCR showed that the mRNA and protein levels of GDF15 were significantly increased in NR5A2 overexpressed pancreatic cancer cells." (PMID 33850096, 2021). "To test if NR5A2 promotes the progression of pancreatic cancer via GDF15, we first carried out MTS, colony formation, and transwell invasion assays in pancreatic cancer cells after GDF15 silencing or overexpression." (PMID 33850096, 2021). "Studies have also shown that NR5A2 cooperates with mutant KRAS to promote pancreatic cancer progression." (PMID 33850096, 2021). "Consistently, BRD4 silencing profoundly decreased NR5A2 expression on mRNA and protein levels in pancreatic cancer cells." (PMID 33850096, 2021). "Taken together, these results demonstrate that BRD4 transcriptionally activates NR5A2 expression in pancreatic cancer." (PMID 33850096, 2021). "To further investigate the mechanisms driving the overexpression of NR5A2 in pancreatic cancer cells, we treated AsPC-1 cells with various inhibitors and examined the changes in NR5A2 expression levels." (PMID 33850096, 2021). "To elucidate how NR5A2 promotes pancreatic cancer progression, we performed RNA-seq analysis in control and NR5A2-silenced PANC-1 cells." (PMID 33850096, 2021). "It is also been reported that NR5A2 overexpression in pancreatic cancer cell lines promoted cell migration, wound healing, cell invasion, and sphere formation." (PMID 33850096, 2021).
pancreatic cancer (continued). "More importantly, we demonstrated that NR5A2 promoted pancreatic cancer progression by upregulating GDF15 expression in vitro and in vivo." (PMID 33850096, 2021). "Overall, our study suggests that BRD4/NR5A2/GDF15 axis is a promising therapeutic target in pancreatic cancer." (PMID 33850096, 2021). "Knockdown of NR5A2 in pancreatic cancer decreased the expression of FGB, TWIST, SNAIL, MMP9, MMP3, MMP2, and Vimentin, as well as increased the expression of the epithelial markers β-catenin and E-cadherin." (PMID 34277436, 2021). "IHC analysis on a TMA of pancreatic cancer samples indicated that there exists a positive correlation between the expression of NR5A2 and GDF15." (PMID 33850096, 2021). "Next, we showed that NR5A2 enhanced the malignancy of pancreatic cancer cells by inducing the transcription of GDF15." (PMID 33850096, 2021). "NR5A2 overexpression induced by BRD4 enhanced the transcription of GDF15 in pancreatic cancer, suggesting that BRD4/NR5A2/GDF15 axis is a potential therapeutic target in pancreatic cancer." (PMID 33850096, 2021). "Colony formation and MTS assays indicated that NR5A2 silencing inhibited the proliferation rate of pancreatic cancer cells." (PMID 33850096, 2021). "NR5A2 silencing inhibited the proliferation and migration abilities of pancreatic cancer cells in vitro and in vivo." (PMID 33850096, 2021). "In conclusion, our study suggests that NR5A2 promoted cell proliferation, migration, and invasion in pancreatic cancer cells." (PMID 33850096, 2021). "Colony formation and MTS assays indicated that NR5A2 overexpression accelerated the proliferation of pancreatic cancer cells." (PMID 33850096, 2021). "In this study, we identified BRD4 as a transcriptional activator of NR5A2 in pancreatic cancer cells and provided another viable strategy to target oncogenic NR5A2." (PMID 33850096, 2021). "We further identified that NR5A2 was transcriptionally upregulated by BRD4 in pancreatic cancer cells and this was confirmed by Chromatin immunoprecipitation (ChIP) and ChIP-qPCR." (PMID 33850096, 2021). "Additional analyses showed two significant gene-environment interactions (between poor oral hygiene and NR5A2 rs2816938 and between obesity and PDX1 rs9581943) on the risk of pancreatic cancer." (PMID 32456644, 2020). "Other studies, although involving factors other than oral hygiene and the NR5A2 gene, have also indicated the role of inflammation in the occurrence of pancreatic cancer." (PMID 32456644, 2020). "We conducted gene-environment analyses with four SNPs (NR5A2 rs2816938, MYC rs10094872, PDX1 rs9581943 and a chromosome 13q22 SNP, rs4885093) significantly associated with pancreatic cancer risk." (PMID 32456644, 2020). "We observed significantly lower mRNA expression of NR5A2 in the majority of pancreatic tumors and cell lines tested compared with histologically normal pancreatic tissue samples, indicating a possible role for reduced NR5A2 expression in pancreatic cancer." (PMID 27579533, 2016). "They found that a full Nr5a2 dose is required to restore pancreatic homeostasis upon damage and to suppress the KRasG12V-driven mouse pancreatic intraepithelial neoplasia progression, indicating that Nr5a2 is a novel pancreatic tumor suppressor." (PMID 25742499, 2015). "The expression of NR5A2 is also elevated in pancreatic cancer and promotes pancreatic cancer cell growth through stimulation of cyclin D1, cyclin E1 and c-Myc." (PMID 25514243, 2014). "Interestingly, it was reported that NR5A2 has critical roles in restraining inflammation in normal mouse pancreas and is considered to be highly relevant to human pancreatitis and pancreatic cancer." (PMID 36961421, 2023). "Our findings establish the crucial role of NR5A2 as a regulator of stemness in pancreatic cancer." (PMID 38012687, 2023). "NR5A2 is over-expressed in pancreatic cancer and promotes EMT." (PMID 36232920, 2022).
pancreatic cancer (continued). "Moreover, the ability of JQ1 to suppress NR5A2 expression in pancreatic cancer cells was dose-dependent and time-dependent." (PMID 33850096, 2021). "In addition, we showed that the expression of NR5A2 in pancreatic cancer cells was regulated by BRD4." (PMID 33850096, 2021). "Hence, we sought to investigate that if NR5A2 promotes pancreatic cancer cell malignancy by activating GDF15 expression." (PMID 33850096, 2021). "In addition, transwell invasion and wound-healing assays revealed that the invasion and migration abilities of pancreatic cancer cells were impaired upon NR5A2 silencing." (PMID 33850096, 2021). "Moreover, NR5A2 overexpression increased the invasion and migration potentials of pancreatic cancer cells." (PMID 33850096, 2021). "A recent meta-analysis has shown that NR5A2 functions as a tumor suppressor in pancreatic cancer." (PMID 34277436, 2021). "Furthermore, GDF15 silencing attenuated cell proliferation, invasion, and wound healing ability in pancreatic cancer cells overexpressing NR5A2." (PMID 33850096, 2021). "NR5A2 silencing inhibited pancreatic cancer cell proliferation, migration, and invasion, we sought to determine whether NR5A2 overexpression would increase tumor cell malignancy by stably overexpressing NR5A2 in AsPC-1 and HPAC cells." (PMID 33850096, 2021). "In addition, analysis of TCGA data indicated that the mRNA level of NR5A2 was relatively high in pancreatic cancer in compare with the most majority of other cancer, except for liver cancer." (PMID 33850096, 2021). "Notably, NR5A2 mRNA level was negatively correlated with the survival of patients with pancreatic cancer and other cancer types (gastric cancer and kidney carcinoma)." (PMID 33850096, 2021). "In addition, our results showed two significant gene-environment interactions (between poor oral hygiene and NR5A2 rs2816938 and between obesity and PDX1 rs9581943) on the risk of pancreatic cancer." (PMID 32456644, 2020). "Interestingly, it has been reported that NR5A2 expression is also increased in pancreatic cancer (see also Suppl." (PMID 28687780, 2017). "Other studies have indicated a growth inducing role for NR5A2 in pancreatic cancer." (PMID 27579533, 2016). "The most notable differences were seen for NR5A2 on chr1q32.1 where mRNA expression was markedly lower in pancreatic tumor samples (average fold change -7.6, P = 5.7×10−8) and cell lines (average fold change -32.7, P = 1.5×10−14) than in histologically normal pancreatic tissue samples." (PMID 27579533, 2016). "Further, NR5A2 expression is elevated in pancreatic cancer andpromotes pancreatic cancer cell growth through stimulation of cyclin D1, cyclin E1 and c-Myc, while genome-wide association studies implicate mutations in the NR5A2 gene in pancreatic ductal adenocarcinoma." (PMID 25514243, 2014). "Moreover, NR5A2 transcriptional activation promotes pancreatic cancer progression." (PMID 35620002, 2022). "Hence, we hypothesized that BRD4 upregulated GDF15 by inducing NR5A2 expression in pancreatic cancer." (PMID 33850096, 2021). "Yet, the precise role of NR5A2 in pancreatic cancer progression remains unclear." (PMID 33850096, 2021). "Hence, our data suggest NR5A2 is a promising therapeutic target in pancreatic cancer." (PMID 33850096, 2021). "These suggested that NR5A2 could be a pancreatic tumor suppressor." (PMID 32456644, 2020). "In our study, we found that GDF15 was transcriptionally induced by NR5A2 and that GDF15 overexpression promoted pancreatic cancer cell proliferation and invasion." (PMID 33850096, 2021). "Previous research suggested an upregulation of NR5A2 in human pancreatic cancer cells compared to non-transformed cells." (PMID 38012687, 2023). "Notably, BRD4 inhibition in pancreatic cancer downregulated GDF15 at the mRNA and protein levels, and GDF15 expression was recovered by NR5A2 silencing." (PMID 33850096, 2021).
pancreatic cancer (continued). "Indeed, BRD4 overexpression in pancreatic cancer cells increased GDF15 expression at both the mRNA and protein levels; this effect was reversed by NR5A2 silencing." (PMID 33850096, 2021). "Western blot and real-time quantitative polymerase chain reaction (RT-qPCR) analysis indicated that NR5A2 levels were higher in pancreatic cancer tissues than in paired nonmalignant pancreatic tissues, both at the mRNA and protein levels." (PMID 33850096, 2021). "In this study, we confirmed that NR5A2 acts as a negative prognostic factor in pancreatic cancer and that NR5A2 promotes cell proliferation, migration, and invasion in pancreatic cancer cells in vitro and in vivo." (PMID 33850096, 2021). "In turn, NR5A2 activates the transcription of GDF15, promoting pancreatic cancer progression." (PMID 33850096, 2021). "In this study, we showed that NR5A2 promoted pancreatic cancer progression by inducing GDF15 expression, suggesting that the pro-tumorigenic roles of NR5A2 and BRD4 in pancreatic cancer could be reversed by GDF15 inhibition, making GDF15 a promising therapeutic target." (PMID 33850096, 2021). "In this study, we found that NR5A2 is a negative prognostic factor in pancreatic cancer and promotes proliferation and migration of pancreatic cancer cells, acting as a negative prognostic factor in pancreatic cancer." (PMID 33850096, 2021). "We were able to show the significant interaction between poor oral hygiene and NR5A2 rs2816938 and between obesity and PDX1 rs9581943, which suggested the involvement of inflammation and metabolic disease-related pathways in the development of pancreatic cancer." (PMID 32456644, 2020). "Therefore, NR5A2 and GDF15 could be promising therapeutic targets in pancreatic cancer." (PMID 33850096, 2021).
colorectal cancer (8 papers, 2007 to 2026). A primary or metastatic malignant neoplasm that affects the colon or rectum. "These images showed that AQP8 and NR5A2 exhibited low staining intensity in colorectal cancer tissues, whereas SCD and TIMP1 showed high staining intensity." (PMID 41438584, 2026). "NR5A2 was identified as a key therapeutic target in colorectal cancer (CRC) through a dual mechanism involving the regulation of NANOG." (PMID 41214698, 2025). "Mechanistically, we establish that NR5A2 transcriptionally activates NANOG to potentiate stemness in colorectal cancer (CRC) cells—a previously unreported regulatory axis." (PMID 41214698, 2025). "In another study, the exogenous overexpression of microRNA‐381 for the obstruction of the function of the NR5A2‐mediated Wnt/β‐catenin signaling pathway led to an increase in the rate of apoptosis in colorectal cancer cells." (PMID 38358044, 2024). "More than half of these were in or near several genes, including cadherin 9 type 2 (CDH9) on 5p14, nuclear receptor subfamily 5, group A gene (NR5A2) at 1q32, gene deleted in colorectal carcinoma (DCC) on 18q21, and PPARG on 3p25." (PMID 17903296, 2007). "MiR-139 reportedly target Rho-kinase 2 in hepatocellular carcinoma 11, NR5A2 in esophageal cancer 14, NOTCH1 and IGF1R in colorectal cancer 15,28." (PMID 26256448, 2015).
diabetes (8 papers, 2011 to 2025). "Furthermore, in a case-only analysis conducted within the PanGenEU study, the overall NR5A2 variation was associated with diabetes (p value = 6.0 × 10−3), suggesting an interaction between both factors in relation to PC risk." (PMID 33517887, 2021). "The authors report that it has been speculated that NR5A2 contributes to diseases linked to pancreatic dysfunction, such as diabetes." (PMID 22125638, 2011). "The Activation of LRH-1/NR5A2 targeting mitochondrial dynamics attenuates the autoimmune attack coupled to beta cell regeneration and islet survival in type 1 diabetes mellitus (T1DM)." (PMID 40866350, 2025). "Our work provide strong evidence that activation of the nuclear receptor LRH-1/NR5a2 using a small chemical agonist, fulfill these requirements and reverts diabetes in several mouse models via an intricate cross talk between islet and immune cells." (PMID 31225479, 2018).